TERT (telomerase reverse transcriptase)
Diseases named in the same sentence as TERT in open-access papers (continued):
Sharing a sentence is not in itself a finding about the gene and the disease.
tumor (continued). "Telomeres length and TERT mRNA expression in HCC and peri-tumor tissues are associated with distinct clinical characteristics." (PMID 36358677, 2022). "Both cfDNA levels (from 1.81 to 1.27 ng/μL) and observed tumor SNVs decreased after that therapeutic intervention, when four SNVs were detected in TERT promoter." (PMID 36010868, 2022). "In tumor cells expressing TERT with BAE, both alleles exhibit hypermethylated UTSS while the hypomethylated proximal TERT promoter." (PMID 36713366, 2022). "With this model, mutated cases with respect to the RPL13A promoter across the cohort closely followed the expected selectively neutral distribution, while TERT showed significant skew toward low-burden tumours." (PMID 36396655, 2022). "The enhanced TERT promoter activity was also demonstrated to be related to betel chewing, tumorigenesis, tumor development, and poor prognosis in OSCC by the previous prevalence studies." (PMID 35875097, 2022). "Specifically, TERT complexes with the chromatin remodeler SMARCA4 to induce the expression of Wnt-responsive genes that promote tumor formation, such as c-Myc and VEGF." (PMID 35159075, 2022). "We found an upregulation of 5p‐end genes including TERT in TCGA tumours with high MKI67 expression, supporting our findings." (PMID 35979662, 2022). "Despite such a high sensitivity and specificity, there exists a potential drawback due to non-tumor derived TERT expression." (PMID 36713366, 2022). "TERT is the catalytic subunit of telomerase, known to be essential for tumor cells to reach unlimited replication potential." (PMID 35619161, 2022). "Conversely, effectors that diminish TERT expression, which include several important tumor suppressors, become dysregulated in cancer cells as a means of de-repressing telomerase activity." (PMID 35159075, 2022). "As expected, IDH-mutant tumors were prevalent predominantly in younger adults, while all IDH-WT/ TERT -mutant tumors apart from a single pediatric tumor occurred in adults." (PMID 34558656, 2022). "The transcription factor GABP is a central node in this pathway, receiving signals from EGFR through AMPK and selectively activating TERT expression, the rate limiting factor in telomerase activity and tumor cell immortality." (PMID 36130485, 2022). "TERT expression and telomeres’ elongation are detected in above 90% of HCC and reported to be associated with tumor aggressiveness and worse patient prognosis." (PMID 36358677, 2022). "Three months later, at a surveillance follow-up, UroAmplitude again detected the TERT/FOXA1 mutations, indicating tumor recurrence that was confirmed by cystoscopy." (PMID 36233691, 2022). "The primary cause affecting the prognosis of PTC include age, tumor size, extrathyroidal extension, lymph node metastasis, distant metastasis, BRAF mutation, TERT mutation, and so on." (PMID 36353231, 2022). "Then, we constructed gene regulatory regression models using MIPRIP to fit gene expression values of TERT across all tumor and all healthy control samples based on the activities of these 75 potential regulators." (PMID 35267575, 2022).
tumor (continued). "In a recent clonal analysis of tumor samples, the amplification of MYCN occurs in ~ 20 to 30%, ATRX mutations or deletions in ~ 10%, TERT mutations in ~ 10%, and MDM2-CDK mutations in ~ 2% of HR-NB." (PMID 36030273, 2022). "Intriguingly, further studies reveal that TC and other tumour cells exhibit monoallelic or biallelic TERT transcription." (PMID 36394204, 2022). "Our results suggest that GABPB1 is required for TERT expression and telomerase activation, but itself serves as a tumor suppressor to inhibit TC progression." (PMID 35326537, 2022). "This suggests that TERT mutations are context specific and only relevant to outcome predictions in IDH1 tumours." (PMID 36042521, 2022). "This is unsurprising since the genetic activation of TERT in an HPV-driven tumour would often be a redundant event (see Section 3.4)." (PMID 36230545, 2022). "Despite readily detectable TERC expression in normal cells, its upregulation occurs widely in TERT‐expressing tumours." (PMID 36394204, 2022). "As expected, somatic mutations in TERT promoter, FGFR3, and CDKN2A identified in the normal urothelium were consistently detected in tumor specimens in many cases." (PMID 36198773, 2022). "The synthetic TERT DNA vaccine works synergistically with anti-CTLA-4 therapy to inhibit tumor growth and prolong survival in mouse models that have a weak response to a single immune checkpoint inhibitor (ICI)." (PMID 35903534, 2022). "The authors used the CRISPR/Cas9 gene-editing method to target the TERT gene in tumor cells, finding that disrupting TERT affects tumor cell viability both in vitro and in vivo." (PMID 35328421, 2022). "AITL, which showed a high frequency of the TERT expression in the current study, is considered a tumor derived from follicular helper T‐cells." (PMID 34477310, 2021). "Regarding pathological tumor differentiation, TERT expression levels were positively correlated with HCC histological grade, while TERT promoter mutations or telomere length were not significantly different between the grades." (PMID 33946181, 2021). "We found TERT-alt in HGMs to be a significant predictor of tumor progression compared to TERT wild-type cases." (PMID 34778063, 2021). "EGR1 has been shown to down-regulate TERT expression and it has been suggested as a tumor suppressor." (PMID 34282050, 2021). "OTX015 and carfilzomib exerted strong synergistic effects to block the overexpression of TERT, induced TERT-rearranged NB cell apoptosis in vitro, and strongly suppressed tumor progression in mouse models." (PMID 34439779, 2021). "Our tumor-subtype evaluations highlighted the various potential modalities of TERT expression changes." (PMID 33924498, 2021). "TERT expression was positively correlated with tumor differentiation and stage progression, and independently predicted shorter time to progression after TACE." (PMID 33946181, 2021). "Significantly higher levels of circulating TERT mRNA were observed 3.5-23.5 months before and close to the diagnosis of cancer as compared to tumor-free patients." (PMID 34746013, 2021). "The TERT expression and telomere length were significantly higher and longer, respectively, in the tumors than in the adjacent non-tumor tissues (all p < 0.001)." (PMID 33946181, 2021). "Intriguingly, T1 and T3 of HCC10 showed distinct branches for these two tumor regions possessed different mutational loci in TSC2, even though they shared a common ancestor in mutations including AXIN1, STK11 and TERT." (PMID 34211467, 2021). "It should be noted that the tumor was positive for BRAF p.V600E (VAF = 15%) and TERT C228T mutations and was reclassified in the ATA high risk category at the last follow-up." (PMID 33821390, 2021).
tumor (continued). "Analysis of quantitative real-time PCR data showed that TERT was upregulated in invasive bladder stages and high tumor grade." (PMID 35223454, 2021). "The sample size used to assess DC in this study was considerably small for determining the significance of TERT and POLD1 mutations for tumor cell dedifferentiation in EC." (PMID 35002543, 2021). "Stratifying by tumor-specific subtypes, we detailed TERT expression differences potentially regulated by subtype-specific molecular characteristics." (PMID 33924498, 2021). "While dox-treated scrambled cells showed continuous tumor growth leading to sacrifice of the mice, we observed disease stabilization after TERT-KD." (PMID 34201898, 2021). "These tumors also harboured distinct EGFR 19Del versus BRAF V601E driver mutations plus multiple unique non-synonymous mutations in each tumor, resulting in a high-probability classification of MPLC with coincidental TERT Amplification." (PMID 34109114, 2021). "The proliferative advantage conferred by TERT reactivation however also has a cost in terms of metabolic alterations, oxygen and nutrient supplies and the tumor microenvironment." (PMID 34944589, 2021). "This reinforces the use of the outlined cancer cell lines in these nine tumor types for TERT isoform research." (PMID 33924498, 2021). "The observation that higher TERT expression levels were an independent factor predicting shorter TTP suggests the tumor-promoting effects of TERT reactivation." (PMID 33946181, 2021). "For the tumor promoter genes SMAD6, TERT, EGFR, and PIK3CA, low levels of expression were associated with better survival, as expected." (PMID 33919332, 2021). "Of note, the variant frequencies in the clonal tumor population (ARID2, SETD2, and TERT promoter) and in the subclonal population (NF2) were validated by targeted NGS for this patient." (PMID 34261524, 2021). "Mutations in ARID1A, ARID2, BRAF, SMARCA4, TERT and IDH1 were significantly exclusive to intracranial metastases while the same variants remained undetected in the corresponding extracranial tumor tissues." (PMID 33578810, 2021). "With tumor stage progression, the TERT level was significantly upregulated (p = 0.005), whereas telomere length significantly decreased (p = 0.011)." (PMID 33946181, 2021). "In contrast, amplification of telomerase reverse transcriptase (TERT) and loss of Cyclin Dependent Kinases Inhibitors (CDKN); CDKN2A/CDKN2B were detected in the tumor." (PMID 34127009, 2021). "Evidence of correlation between methylation and tumour TL in TERT led us to investigate the role of methylation on TL genome-wide." (PMID 34824250, 2021). "The tumor suppressor p73 also interacts with Sp1 to suppress TERT while activation of TERT is mediated by p73β expression." (PMID 34440361, 2021). "Except for TERT and CLPTM1L, genes shared by neoplasm diseases and other diseases in the two modules are different, reflecting diverse mechanisms underlying neoplasms of different tissues and their multimorbidities." (PMID 34225788, 2021). "At an isoform level, while tumor samples had higher TERT_238.6 expression, they typically had lower TERT_238.6 isoform percentage, indicating a shift in splicing away from FL-TERT." (PMID 33924498, 2021).
tumor (continued). "Conversely, a significantly increased TERT expression was observed in tumor samples, indicating they relied on reactivating canonical telomere maintenance." (PMID 34867976, 2021). "The approach was achieved by using TERT activity, which maintains the unlimited replication potential of tumor cells, as a positive screening marker combined with the negative screening of CD45 antibody markers." (PMID 33905377, 2021). "TERT expression is correlated with telomerase activity, and canine TERT promoter (cTERTp) activity is upregulated in most canine tumor cells compared to that in normal canine cells." (PMID 34408176, 2021). "In contrast and in terms of polyclonal events, tumor associated urothelium, non-invasive urothelium lesions and CIS demonstrated a different TERT promoter mutation compared to the MIBC." (PMID 33562516, 2021). "Together with the tumor stage, high levels of TERT expression (HR = 2.06, 95% CI: 1.06–4.01, p = 0.033) were identified as an independent predictor of shorter TTP after TACE." (PMID 33946181, 2021). "The frequency of recurrent HBV integration into TERT or MLL4 was particularly high in tumor samples, accounting for 54.5% (12/22) of HBV-related HCC with integrations." (PMID 34209079, 2021). "Overall, the TERT gene and its function were markedly altered in the tumors compared to the adjacent non-tumor samples." (PMID 33946181, 2021). "The approach exploits a blood biopsy to detect circulating tumour DNA (ctDNA), which can be a simple way to test for MRD, based on assessment of BRAF, NRAS, or TERT mutations that are present in more than 75% of melanoma patients’ tumours." (PMID 36284898, 2021). "It is impossible to know if the tumor even showed a TERT rearrangement since only a-CGH data were available; however, these rearrangements are almost mutually exclusive with MYCN amplification." (PMID 34830942, 2021). "While a TERT promoter mutation is not found in conjunctival nevi, it is found in both PAM and CM, with increased TERT expression leading to tumor progression." (PMID 34071371, 2021). "Telomerase reverse transcriptase (TERT) is a self-tumor antigen that plays a major role in tumor development and progression, and is overexpressed in more than 90% of human tumors." (PMID 34144673, 2021). "Further, tumor cells harvested from the MJ group displayed a significantly declined Hsp70, Bcl-2, and TERT expression." (PMID 33718176, 2021). "Another study showed that TERT can increase tumor immunogenicity and affect the response to ICI therapy." (PMID 35223454, 2021). "Consistent with previous studies TERT expression is upregulated in a variety of tumor cells and its reactivation is a key step in the development of cancer." (PMID 33763172, 2021). "It is necessary in telomerase reverse transcriptase (TERT) expression, a factor required for immortalization of tumor cells." (PMID 34925377, 2021). "Epigenetic and genetic factors both have roles in determining TERT expression levels in tumour cells." (PMID 33802026, 2021). "To this end, we measured by IFN-γ ELISpot the CD4 T cell response directed against telomerase (TERT), a shared-tumor antigen." (PMID 34144673, 2021). "Spontaneous T-cell responses to EBV, CMV and tumor associated antigens, EBV-DNA and CMV-DNA loads, and circulating TERT mRNA levels were investigated." (PMID 34746013, 2021). "Through analysis, we identified distinct patterns of HBV integration and TERT alterations between tumor and non-tumor tissues as well as the biological functions of genes with HBV integrations in HCC." (PMID 34209079, 2021). "Epigenetic modifications through promoter methylation, histone acetylation and methylation, transcriptional and posttranscriptional mechanisms, and non-coding RNAs all also contribute to the regulation of TERT expression in human tumour cell lines." (PMID 33802026, 2021).
tumor (continued). "To aid future investigations and navigate the heterogeneity of TERT transcriptomes, we attempted to find suitable cancer cell lines for primary tumor types." (PMID 33924498, 2021). "In contrast, the overexpression of TERT was previously identified in 73% of all cancers by systemic analysis of TERT gene amplification in the Cancer Genome Atlas (TCGA) cohort including 6835 patients and covering 31 tumor types." (PMID 34439779, 2021). "TERT is also a broad-spectrum tumor marker, which is conducive to the excessive division of tumor cells." (PMID 34124154, 2021). "To fully define TERT isoform expression heterogeneity, we evaluated the tumor-specific subtype-dependent differences." (PMID 33924498, 2021). "All radiomic features selected for identifying TERT status were tumor-related, which differed from the feature spectrum of IDH and 1p/19q status." (PMID 34312469, 2021). "Telomere shortening leads to reactivation of telomerase, promoting survival of tumor cells and “TERT addiction” of liver tumors." (PMID 34067686, 2021). "The methylation of THOR was detected in 90% of cases mainly of advanced tumor stage and high grade with hypermethylated patients displaying the highest TERT mRNA levels." (PMID 35223454, 2021). "The results showed a strong synergistic effect of the two drugs in blocking TERT overexpression, inducing NB cell apoptosis in vitro, and drastically reducing tumor progression in murine models." (PMID 34072462, 2021). "Albeit differences in expression relationships, normal tissue types with greater total TERT expression, such testicular tissue and the gastrointestinal tract tissues, more closely approximated what was observed in tumour tissues." (PMID 33924498, 2021). "Aberrant telomerase reverse transcriptase (TERT) expression is crucial for tumor survival and cancer cells escaping apoptosis." (PMID 34858826, 2021). "The TERT promoter is an exception to this model due to its hypermethylated promoter pattern found in most tumour cells and accompanying robust expression." (PMID 33802026, 2021). "Reduced level of TERC is sufficient to cause telomere diseases, such as dyskeratosis congenita, aplastic anemia, and idiopathic pulmonary fibrosis while up regulation of TERT expression have a critical role in tumor formation and chemotherapy outcome." (PMID 34048184, 2021). "Upon reactivation, TERT binds to the promoter region and induces the transcription of miR500A in tumour cells." (PMID 33713376, 2021). "The common variations include loses in 22q (includes NF2 and CHEK2) and 10q, and gains in 1q and oncogenic drivers BRAF (in BRAF wild-type tumours) and TERT." (PMID 34062862, 2021). "To explore the relationship of TERT RNA abundance and tumour TL further, we considered known activating transcription factors." (PMID 34824250, 2021). "Taken together, our work has reinforced the need for tissue and tumour-specific TERT investigations, provided avenues to do so, and brought to light the current technical limitations of bioinformatic analyses of TERT isoform expression." (PMID 33924498, 2021). "Nevertheless, TERT expression became significantly enhanced with the progression of tumor stage and tissue differentiation, which was eventually linked to tumor progression in TACE-treated patients." (PMID 33946181, 2021). "We did not observe any TERT promoter mutations in our cohort but there are strong negative correlations between methylation probes in the promoter of TERT and tumour TL." (PMID 34824250, 2021). "TERT was undetectable in healthy bladder tissues but upregulated in invasive BC stages and high tumor grade." (PMID 35223454, 2021). "Next-generation sequencing identified amplification of TERT and loss of CDKN2A/CDKN2B in the primary tumor." (PMID 34127009, 2021).